IL6 (interleukin 6)
Diseases named in the same sentence as IL6 in open-access papers (continued):
Sharing a sentence is not in itself a finding about the gene and the disease.
cancer (continued). "Our results showed that IL-6 stimulated STAT3 phosphorylation on tyrosine 705 in DLD1 and Hep3B cancer cells." (PMID 26883202, 2016). "Our data highlight a functional role for interleukin-6 in cancer dissemination via MMP-14 and pose a new rationale for therapeutically targeting the IL-6 signaling pathway in cancer." (PMID 27531896, 2016). "In addition, the involvement of certain interleukins including IL-6, IL-4, IL-17A and IL-32β in some EMT pathways signifies their specific contribution in metastastic processes, thereby warranting further work into the development of diagnostic and immunotherapeutic tools in cancer." (PMID 25590298, 2015). "IL-6 contributed to upregulation of genes related to CSCs and cell proliferation as well as activation of JAK2/STAT3 in cancer cells." (PMID 25797257, 2015). "As expected, strong correlations between levels of IL-6, TNF-α, IL-1β, VEGF, MMP-9 and TF in plasma from cancer patients DVT+ and DVT- and those released from monocytes of the same patients were observed." (PMID 26192925, 2015). "Flagellin stimulates immune responses by upregulating TNF-α and IL-6 and activating PI3K in epithelial cells and cancer cells." (PMID 25942007, 2015). "A growing body of studies suggests that NF-kB activation mediates up-regulation of inflammatory cytokines, angiogenic factors (e.g. CRP, IL-6, TNF-α, IL-1β, VEGF, MMP-9) in cancer." (PMID 26192925, 2015). "Consistent with previous reports, significant upregulations of IL-1β, IL-6, and TNF-α mRNAs in the cancer group compared to the naive group were observed." (PMID 26649065, 2015). "In this study we have found that Hs738 gastric stromal cells secrete IL-6 and GAPDH for positive and negative regulation of cancer cells, respectively." (PMID 25785838, 2015). "Being a crucial member at the crossroad between inflammation and cancer, SAG appears to be an important modulator of proinflammatory/protumorigenic molecules (IL-1β, IL-6 and TNF)." (PMID 27551463, 2015). "In the high IL-6 expression group, IL-6 receptor (IL-6R), phospho-signal tranducer and activator of transcription 3 (p-STAT3) were also detected in almost all the cancer cells." (PMID 25761055, 2015). "This is particularly relevant in the context of inflammation-induced cancer, where STAT3 is known to play a major role, consistent with the observation that persistent IL-6 production and STAT3 activation are prominent features of chronic inflammation." (PMID 26106584, 2015). "Interleukin-6 (IL6) is a pleiotropic cytokine expressed by immune cells and a great variety of cancer cells." (PMID 26215971, 2015). "We observed the relationship between GZMM expression and the secretion of IL-6 and VEGF from cancer cells for the first time." (PMID 25788270, 2015). "Inflammatory cytokines such as tumor necrosis factor-α (TNF-α), interleukin-1 (IL-1), interleukin-6 (IL-6), and interferon-γ (IFN-γ) are involved in the pathogenesis of cancer cachexia." (PMID 26451159, 2015). "Higher mean levels of IL-6, TNF-α, IL-1β, VEGF, MMP-9 and TF were secreted from healthy monocytes treated with the sera derived from cancer patients DVT compared to those from DVT- (p<0.01)." (PMID 26192925, 2015). "Several well-established cachectic cytokines are elevated in the sera of cancer patients, including TNF-α, IL-6, and myostatin." (PMID 25972815, 2015). "Positive correlations (|r|>0.45) among CRP, IL-6, TNF-α, IL-1β, MMP-9, VEGF, and TF antigen were found in both groups of cancer patients, whereas the fibrinogen correlated only in DVT+ group." (PMID 26192925, 2015). "STAT3 activation is able to directly affect the expression of IL-6, which is also one of the key STAT3 activators during cancer EMT progression." (PMID 25788270, 2015).
cancer (continued). "Synthesis of both insoluble (e.g. collagen I) and soluble (e.g. IL-6) proteins secreted by CAFs is turned off upon inhibition of mRNA translation, providing a novel strategy to prevent CAF-mediated drug resistance in cancer cells." (PMID 25834145, 2015). "IL-1, IL-6, and TNF-α are secreted in the inflammatory settings of cancer and induce immune cell proliferation, survival, activation, and infiltration of the tumor to execute the antitumor immune response." (PMID 26528286, 2015). "Moreover, our results suggest that high serum resistin levels are related to cancer-associated chronic inflammation and support the previous study in which resistin exhibited pro-inflammatory properties by up-regulating the expression of TNF-α and IL-6 and the activation of monocytes." (PMID 26690142, 2015). "Some cancer cells express CRP and secrete interleukin-6 and interleukin-8, which stimulate liver CRP production." (PMID 26717416, 2015). "Cancer-related fatigue is correlated with markers of inflammation (C-reactive protein, IL1-receptor antagonist, IL-6)." (PMID 26469939, 2015). "Basal B-type cancer cell lines with a mesenchymal phenotype showed the highest expression of the YAP targets, IL6 and CTGF." (PMID 26671411, 2015). "On IL6 pre-treatment, number of ALDH1+ cells increased in all three (MDA-MB 231, MDA-MB 468 and MCF7) cancer cells." (PMID 25973915, 2015). "IL-6, IL-8, MCP-1, RANTES, SDF-1, TGF-β1, and VEGF, among others, can shift BCCs to a more aggressive cancer phenotype, resulting eventually in increased metastatic occurrence." (PMID 26000019, 2015). "Mediators secreted by these cells that directly or indirectly promote cancer cell growth include cytokines, chemokines, and growth factors, such as VEGF-A, CSFs, IL-1, IL-6, IL-8, or CXCL1." (PMID 26343581, 2015). "Among the cytokines released within the tumor microenvironment, interleukin (IL)-6 plays a pivotal role in CCA pathogenesis, as a potent stimulator of cancer growth and progression." (PMID 26296968, 2015). "Intrathecal administration of 100 μg BE reversed the upregulation of IL-6 and TNF-α observed in the cancer group at the 2nd h after injection." (PMID 26649065, 2015). "IL-6 induces and maintains the EMT through feed-forward loops in a variety of carcinomas, including breast." (PMID 26512918, 2015). "We also document that like basal-like carcinoma cells, T-MS also express the CK-5/14, EGF-R, CD133, Bmi-1, and IL-6 genes." (PMID 25881039, 2015). "Coincidently, we found that protumorigenic/proinflammatory cytokines, IL-1β, IL-6 and TNF, along with SAG, were significantly upregulated in the primary carcinoma tissues (P<0.01)." (PMID 27551463, 2015). "In the whole panel of cytokines, only IL-1β, IL-2, IL-6, TNF-α, IL-8, and MCP-1 were found to be modified in cancer patients after RT." (PMID 24800238, 2014). "Second, it has been shown that both un-phosphorylated STAT3 and STAT3-DN can interact with NFκB in the nucleus to drive the expression of multiple cancer-related genes, such as RANTES, IL-6, IL-8, MET and MRAS." (PMID 24995504, 2014). "Unfortunately, increasing levels of interleukin-6 (IL-6) (25.41 vs 16.03 pg/mL) and carcinoembryonic antigen (CEA) (23.43 vs 7.13 ng/mL) indicated cancer progression, which was confirmed by the presence of multiple metastases in both lungs on CT scan images." (PMID 24885608, 2014). "Elsewhere, elevated serum cytokines and/or chemokines have been observed in cancer patients (such as TNF-α and IL-6), whilst others, like IL-12, are often down-regulated." (PMID 24520352, 2014).
cancer (continued). "Inflammation is implicated in the progression of different haematological or non-haematological malignancies, and several pro-inflammatory factors, such as IL-6 and TNF-α, play a role in cancer development or progression." (PMID 24778454, 2014). "In cancer cachexia, systemic inflammation is induced and persists due to increased tumor necrosis factor-alpha (TNF-α), interleukin-6 (IL-6), IL-1, and interferon-gamma (IFN-γ)." (PMID 25050383, 2014). "CD40L inhibits in vitro melanoma cell proliferation by inducing their apoptosis or stimulating the production of cytokines that activate the immune system (IL-6, IL-8, TNF-α) by cancer cells." (PMID 25117071, 2014). "Further investigation indicated that the IL-6/JAK2/STAT3 pathway was preferentially active in CD44+CD24− breast cancer stem cells, and inhibition of JAK2 decreased the number of cancer stem cell number and blocked the growth of xenografts in mice." (PMID 24995504, 2014). "In fact, the experience we have gained with the BALB-neuT model suggests that some of the molecules released by MSCs, such as IL-6, TGF-β, and HMGB1, are key molecules in CSC self-renewal and cancer progression." (PMID 25136593, 2014). "It is possible that cytokines such as IL-6 enhance AMPK activation and through this mechanism, stimulate lipid mobilization from WAT during cancer cachexia." (PMID 24667661, 2014). "Thus, IL-6 may be a good candidate for engineering DCs for cancer immunotherapy." (PMID 24690994, 2014). "Inhibiting IL-6/JAK/STAT3 signaling or STAT3 activity alone with antisense oligonucleotides, siRNA, or small-molecule inhibitors can dramatically sensitize cancer cells to treatment with EGFR inhibitors." (PMID 24662938, 2014). "STAT3 signaling in MDSC can be modulated by IL-6, which has been shown to enhance CSCs and EMT in cancer." (PMID 24652403, 2014). "Contrary to those studies, no change in mRNA expression of inflammatory markers including IL-6 and TNF-α were observed in SAT from cancer patients or in an animal model." (PMID 25415607, 2014). "The involvement of the JAK-STATs signaling pathway in IL-6/IL-6R signaling and involvement of STAT3 phosphorylation in EMT of cancer cells has been proved by lots of results." (PMID 24789104, 2014). "Several lines of evidence in this study showed that, in addition to its role in leukocyte adhesion and cancer cell invasion, ICAM-1 plays an important role in IL-6-mediated cancer metastasis." (PMID 24398980, 2014). "This patient, whose diagnosis was large cell carcinoma with cancer cachexia, suffered a performance status (PS) that deteriorated to an ECOG score of 4 with an increase of serum IL-6 to 173 pg/ml." (PMID 25010770, 2014). "It is also noteworthy that, compared to ASCs-CM, hUCESCs-CM contain lower levels of factors known to participate in cancer progression, such as EGFR, FGF 4 and 9, ICAM3, IL6, IL6R, MCP3 (CCL7), MIF, sgp130 and VEGFD." (PMID 25296979, 2014). "IL-6 has multiple effects on RANK, TGFβ and Wnt signal cascades and the control of these pathways by IL-6 results in degradation of bone that facilitates cancer metastasis to this site." (PMID 24722453, 2014). "Thus, IL-6 may be a good candidate for engineering DCs for effective cancer immunotherapy." (PMID 24690994, 2014). "IL-6 and MMP-9 promote invasion and metastasis of cancer cells via accelerating ECM degradation, inflammation, angiogenesis and proliferation." (PMID 25058006, 2014). "Several inflammatory mediators, such as TNF-α, IL-6, TGF-β, and IL-10, have been shown to participate in both the initiation and progression of cancer." (PMID 24901008, 2014). "Cancer inflammation is activated by several inflammatory cytokines such as TNF-α, IL-1, IL-6, IL-8, and IL-18." (PMID 24976685, 2014). "Network analysis shows that the genes harboring disruptive SNVs were involved in molecular mechanisms of cancer, and the signaling pathways of LPS-stimulated MAPK, IL-6, iNOS, EIF2 and mTOR." (PMID 24416147, 2014).
cancer (continued). "The relationship between IL-6 and IFN-γ is striking given the often distinct roles of STAT1 and STAT3 in inflammation and cancer." (PMID 24412616, 2014). "To show the AGM-inducing factors in cancer vasculature, we investigated effects of TNF-α, TGF-β, VEGF, IL-6, and IL-8 on the expression of AGM protein by HUVECs in vitro." (PMID 24737780, 2014). "Among the genes upregulated in GFPHigh cells are cytokines (IL-6, IL-8, or TNF) and transcription factors (KLF6, ATF3, SNAI2) that have been previously related with cancer stemness, cellular plasticity, or both." (PMID 25414831, 2014). "For example, patients with melanoma have an increased relapse-free survival if short-term cultures of their cancer cells retained a sensitivity to OSM and/or IL-6." (PMID 24675570, 2014). "Thus, AP-1 activation might be one of the mechanisms for IL-6 overexpression in cancer cells." (PMID 23592411, 2013). "TTP also has multiple important targets, including COX-2, HIF-1α, IL-8, IL-6, IL-8, and VEGF 34,36–40 and the oncogenic Ser/Th kinase Pim-1, which is overexpressed in several cancers and promotes cellular growth and apoptosis resistance 41,42." (PMID 23401122, 2013). "IL-6 and TNF-α are pleiotropic cytokines that function as autocrine or paracrine growth factors, which are secreted by normal prostate epithelial and cancer cells." (PMID 24168453, 2013). "Thus, IL-6 from cancer cells may play a central role in EGFR-TKI-induced interstitial pneumonia." (PMID 23592411, 2013). "It is important to note that IL-6 and IL-10, TNF-α, and IL-1β have been implied in the generation of the MDSCs, which are commonly found in cancer patients." (PMID 23616009, 2013). "The overproduction of selective cytokines such as interleukin-6, tumor necrosis factor α, and CRP has been shown to play a key role in inducing chronic inflammation in cancer patients." (PMID 24244659, 2013). "The gene expression data derived from the OSCC biopsies that showed upregulation of IL6 and IL8 and downregulation of IL12A were used to mimic inflammation in oesophageal epithelial and cancer as well as control cell lines." (PMID 23570247, 2013). "Thus, IL-6 might represent a promising therapeutic target for preventing radioresistance of cancer." (PMID 23806095, 2013). "Apart from IL8, the co-regulation between NF-κB and AP1, CEBPB or STAT3 for genes IL1B, ICAM1, IL6, PTGS2, and SAA1 in the TF regulatory networks is consistent with previous observation in HNSCC or other cancer cells." (PMID 24069219, 2013). "Previous studies have indicated that Cygb loss was associated with increased cancer cell proliferation and overexpression of IL-1, IL-6, VEGF, TNFα, and TNFb mRNAs in cancer development in the liver and lungs of mice exposed to N,N-diethylnitrosamine." (PMID 23688241, 2013). "Specifically, the up-regulation of IL-6 and IL-8 has been suggested to play important roles in the development and progression of OSCC and other cancers." (PMID 23762476, 2013). "For example, the pro-inflammatory cytokines TNF-α, IL-6 and IL-8 can induce EMT and promote cancer metastasis." (PMID 23922983, 2013). "Since tumors are possible sources for inflammatory cytokines like IL-6 and TNF-α, analyses were repeated after excluding 8 patients who developed cancers within one year from baseline, to reduce the effect of a preclinical malignancy." (PMID 24205276, 2013). "The upregulated cancer inducing factors probed here include EMMPRIN, MMP-9, IL-6, and TGF-β1 and all were secreted upon stimulation with EVs used here." (PMID 23936495, 2013). "We found up-regulation of glycolysis and lipid metabolism and up-regulation of acute phase response signalling including increased levels of IL6, demonstrating that those mechanisms are relevant in HFD induced bladder pathophysiology." (PMID 23826106, 2013). "Specifically, IL-6 and IL-8 were recombinantly produced and purified since, like PPIA, these cytokines are involved in both inflammation and cancer progression." (PMID 22631225, 2012).
cancer (continued). "Despite improved understanding of IL-6′s role in inflammation and chronic disease, there are limited data on the effect of IL-6 on CVD, cancer, and liver-related mortality in a large population-based cohort." (PMID 22514624, 2012). "Because the highest levels of IL-6 occurred at the onset of SCC induction, it is possible that this cytokine plays a role in cancer establishment in our model." (PMID 23176085, 2012). "The study of STAT3 in cancer has revealed that JAK2/STAT3 was activated in starved Hela cells, with the activated STAT3 directly bound to IL-6 promoter to increase IL-6 mRNA and protein secretion." (PMID 22937006, 2012). "MCF-7 and ASPC-1 cancer cells, which expressed low level of phosphorylated STAT3, were pre-treated with XZH-5 for 2 hours followed by the addition of IL-6." (PMID 23056374, 2012). "As with DMXAA-regulated stromal RNAs, several cancer cell-derived RNAs, including CCL2 (MCP-1), IL-8, IL-6, CXCL1 (Melanoma Growth Stimulating Activity/GRO1), also concurred with the protein data." (PMID 22415295, 2012). "Previously, we have reported changes in the inflammatory cytokines IL-6, MCP-1, VEGF, KC, and MIP-2 in the culture supernatants from femurs of athymic mice three weeks after intracardiac injection of MDA-MB-231 cancer cells." (PMID 22315691, 2012). "JAKs are the principal mediators of IL-6/gp130/STAT3 signaling and, in several cancer models, JAK inhibitors' anti-tumorigenic effects are mediated by STAT3." (PMID 23056499, 2012). "Fenugreek blocked activation of NF-KB, I kappa B kinase and AKT and suppressed the production of various proinflammatory cytokines like IL-6, IL-1 and TNF-α by cancer cells." (PMID 23110539, 2012). "JAKs are tyrosine kinases that mediate IL-6- dependent STAT3 activation, which has been shown to promote cancer progression in numerous examples of solid tumors." (PMID 23056499, 2012). "In the present study, we confirmed a higher expression level of the examined genes (for PD-L1, Galectin-1, IL-6, IL-10, IDO, and TGF-β) in the cancer patients." (PMID 22496728, 2012). "From the ELISA consequence of cytokines as markers of cancer-related fatigue, the concentrations of TNF-α and IL-6 after treatment were significant lower than these before treatment." (PMID 22203880, 2012). "To reconfirm previous reports that IL-6 induces proliferation of cancer cells, we serum-starved NCI-H446 and NCI-1688 cells for 12 h and then cultured them in the absence or presence of different concentrations of IL-6 for 24 h, 48 h and 72 h." (PMID 22662257, 2012). "While JAK2 mutation is a common means to stimulate oncogenic STAT activity, perturbations in other signaling networks, such as those mediated by EGFR, IL-6/IL-6R or FLT3, can also contribute to activated STAT signaling in cancer cells." (PMID 21533169, 2011). "The first description of STAT3 in 1994 raised suspicion in the direction of cancer because IL-6 and EGF, already recognized to have cancer connections, were the originally recognized ligands that activated the STAT3 homodimer." (PMID 21149895, 2010). "In our study, however, knocking-down Stat3 with Stat3 siRNAs resulted in a decrease in IL-6 expression in AS2 cells and two drug resistant cancer cell lines (KB-CPT100 and MCF-7/ADR)." (PMID 21122157, 2010). "In the current study, we demonstrate that hBD-3 can promote macrophage expression of IL-1α, IL-6, IL-8, and CCL18; i.e., cytokines and chemokines that are produced by TAMs as components of the cancer-related inflammation." (PMID 20544025, 2010). "In contrast, co-cultures of cancer stem cells with NK cells demonstrated increased IFN-γ in the context of lower GM-CSF, IL-6 and IL-8 secretion." (PMID 20661281, 2010). "We examined the cytokines secreted by MDA-MB-231 cells in culture supernatants involving IL-6, TGF-β, VEGF and MMP9 which are required for cancer cellular invasion and metastasis." (PMID 20520770, 2010).